ARG1 (arginase 1)
Diseases named in the same sentence as ARG1 in open-access papers (continued):
Sharing a sentence is not in itself a finding about the gene and the disease.
tumor (continued). "ARG1 possesses a hierarchical negative function compared to that of iNOS in establishing an immunosuppressive TME, as iNOS-expressing cells such as tumour-infiltrating M1-polarised macrophages and Tip-DCs (a DC subset that releases TNF and NO) are actively involved in tumour debulking." (PMID 34685679, 2021). "Moreover, after adjustment for tumor purity, FUNDC1 in LIHC had no relation to M1 macrophages but negatively correlated with ARG1+ M2 macrophages, while FUNDC1 in LUSC negatively correlated with ROS+ M1 macrophages and MRC1+ M2 macrophages." (PMID 31998650, 2019). "Finally, Arg1, involved in the immunosuppressive function of MDSC, was found to be highly elevated in the draining lymph nodes of tumor bearing metastatic and non-metastatic Stat4−/− mice compared to tumor bearing WT counterparts." (PMID 32010142, 2019). "We employed IHC and flow cytometry because the M2 and M1 markers are also ubiquitous enzymes (iNOS and ARG1) and cytokines (IL10 and IL12) which can be expressed by other Iba1(−) cell types (non-TAM, including other immune cells) in the GBM tumor microenvironment." (PMID 30041669, 2018). "Interestingly, pulmonary MDSCs from 4T1 tumor-bearing SHIP−/− mice, but not WT mice, displayed Arg1 expression." (PMID 26683227, 2016). "Immunohistochemical analysis of tumor cells indicated the following: HMB-45(+); vimentin(+); smooth muscle actin (SMA)(+); melan-A(+); CK(−); hepatocyte(−); Arg-1(−); GPC-3(−); CK7(−); CK19(−); CK20(−); S-100(−); CD34 blood vessel endothelium(+); and no exact tumor suppository." (PMID 26698563, 2015). "As a component of the tumor immune microenvironment, MDSCs and their related factors and functions, such as reactive oxygen species (ROS), indoleamine 2,3-dioxygenase (IDO), arginase 1 (ARG1), adenosine, and negative immune checkpoints, can remodel the suppressive immune microenvironment of tumors." (PMID 36978204, 2023). "Although IL4Rα-negative MDSC had lower Arg-1 and NOS2 expression before and after chemoradiotherapy, the possibility remains that they may transform into more suppressive cells upon entering the tumor microenvironment." (PMID 37554225, 2023). "Immunohistochemical staining showed that the tumor cells were negative for AE1/AE3, CK18, CK7, Hepatocyte Paraffin-1(Hep Par-1), Glypican-3 (GPC-3), Arginase-1 (ARG-1), CD56, Chromogranin A (CgA), Synaptophysin (Syn), Vimentin, and Carcinoembryonic antigen (CEA)." (PMID 31488173, 2019). "We hypothesize that the production of arginase-1 by TAMs in MCA-205-OVA or MCA-205-E1A-Δp300-OVA tumor cells leads to an ineffective anti-tumor immune response in the tumor microenvironment, but does not result in inhibition of a systemic anti-tumor immunity." (PMID 24614600, 2014).
cancer (325 papers, 2011 to 2026). A tumor composed of atypical neoplastic, often pleomorphic cells that invade other tissues. "We find that high ARG1 level is associated with weight loss and shorter survival of cancer patients." (PMID 40474277, 2025). "ARG1 level in patients’ plasma was evaluated using ELISA, and the association between ARG1 level and patient survival, across multiple types of cancer, was examined using the online database Kaplan-Meier plotter." (PMID 40474277, 2025). "Together, these findings support an association between elevated arginase 1 levels, cachexia, and poor survival outcomes in cancer." (PMID 40474277, 2025). "ARG1 is able to activate immunosuppressive cells such as MDSCs, which have the ability to suppress T cell activity and cause the escape of cancer cells from the immune response." (PMID 39337272, 2024). "To corroborate the results above, we also considered levels of mRNA expression of the arginase-1 enzyme, which is highly expressed in MDSCs and linked to their suppressive function in cancer." (PMID 39337370, 2024). "Cancer-derived SPP1 is linked to MDSC (myeloid-derived suppressor cells) immunosuppression by regulating arginase 1, NOS2, VEGF, and IL-6." (PMID 38491408, 2024). "In various cancer types, increased expression of presumably dysfunctional ARG1 was associated with poor overall survival rates, development of suppressive M2-like phenotype, and an immunosuppressive microenvironment." (PMID 39712018, 2024). "Both gene expressions were closely associated with ARG1 expression and FoxP3 expression, respectively, in cancer str of the CRC tumors." (PMID 38557819, 2024). "In the present study, ARG1 expression was evaluated as a potential prognostic marker for metastatic EC in endometrial hyperplasia and cancer of mice with Pten mutation as well as Pten and Mig-6 double mutations." (PMID 37503068, 2023). "In humans, high ARG1 expression and activity have been reported in many cancers, often associating a high ARG1 expression with poor prognosis." (PMID 37980483, 2023). "In particular, the T cell activation genes Rac2 and Igf1 were increased while the malignant tumor-associated genes Mgl2, Tnfrsf9, Vegfa as well as the M2 macrophage markers Retnla and Arg-1 were decreased." (PMID 37925462, 2023). "ARG1, arginase-encoding gene, was reported to be upregulated in the peripheral blood and cancer tissue of various cancer patients." (PMID 34480465, 2022). "Arginase 1 activity promotes cancer growth, spread, and angiogenesis and has been associated with a poor prognosis in various types of cancer." (PMID 36483029, 2022). "For instance, sweeping changes were observed in the amino acid residues of arginase 1 (ARG1), which functions in the urea cycle, and increased ARG1 activity has been linked to certain pathologies including human cancer." (PMID 34733838, 2021). "Cancer-associated upregulation of arginase -1 contributes to a diminished extracellular arginine pool." (PMID 32872669, 2020). "Depletion of arginase 1-expressing PMN-MDSCs within these co-cultures rendered the organoids susceptible to anti-PD-1/PD-L1-induced cancer cell death." (PMID 33348809, 2020). "Our findings in current study indicate the important diagnostic specificity of Arg-1 in cancer patients on fine-needle aspiration specimens." (PMID 32854754, 2020). "Most studies point out that the suppressive role of MDSCs in cancer is associated with the activation of their two enzymes, namely inducible NO synthase (iNOS) and arginase-1 (ARG1)." (PMID 32849517, 2020). "On the other hand, all cancer patients showed a diagnostic response to both proteins and apparently, Arg-1 can easily and reliably replace HepPar-1 in cancer diagnostic processes." (PMID 32854754, 2020). "This hallmark of T-cell dysfunction can also be observed in cancer patients in association with increased plasma activity of Arg1 released by myeloid-derived suppressor cells (MDSCs)." (PMID 33392202, 2020).
cancer (continued). "Arg1-expressing MDSCs are prominent immunosuppressors implicated in the pathogenesis of chronic helminth infection, autoimmune diseases and graft-versus-host disease, as well as in cancer." (PMID 34037806, 2021). "Interestingly, we did not see an increase in expression among genes that are associated with immunosuppression in cancer (such as ARG1, CD274, COX2, PGE2, and NOS2)." (PMID 33659259, 2020). "Emerging therapies-such as ARG1 inhibitors, engineered extracellular vesicles, and microbiome interventions-show preclinical promise in cancer, cardiovascular, and neurodegenerative diseases." (PMID 41939876, 2026). "Utilizing ex vivo approaches, we showed that secreted factors from cancer cells induced the expression of multiple cytokines in lung fibroblasts, and in turn drove expression of immunosuppressive factors, such as arginase 1, in macrophages." (PMID 39782689, 2025). "Highly expressed ARG1 in cancer cells directly impairs T cells function by depleting L-arginine in TME." (PMID 40659985, 2025). "Based on the observations that arginase inhibits T cell in the tumor microenvironment and thus promot cancer growth, novel immunotherapy vaccines targeting Arg1 or Arg2 have been developed and are now undergoing clinical trials." (PMID 39952693, 2025). "Specifically, we found a positive correlation between cancer cell PS exposure and the quantity of secreted M2 markers, such as arginase 1 and TGM2." (PMID 40227806, 2025). "For all these cancers, high expression of ARG1 predicted poorer overall survival with a hazard ration ranging from 1.22 to 1.67." (PMID 40474277, 2025). "In general, one major mechanism of CD8+ T-cell suppression by TAMs is the depletion of metabolites essential for T-cell proliferation, such as l-arginine, which is depleted by TAM-derived arginase-1 in various cancers." (PMID 39969434, 2025). "In cancer, they emerge as master regulators of immune evasion, deploying metabolic warfare through arginase-1 expression and creating immunosuppressive niches via PD-L1." (PMID 41301697, 2025). "In conjunction with our observed increase in macrophage SREBP1, there were simultaneous increases in Arg1, Cxcl5, and Il6, all of which can promote cancer progression in different cancers." (PMID 41462606, 2025). "The characteristic markers of these macrophages (such as CD206 and Arg1) are highly expressed in cancer tissue, further corroborating the pivotal role of M2 macrophages in transforming inflammation into cancer." (PMID 40109347, 2025). "For cancer vs. non-cancer prediction, the top-performing model included the plasma concentrations of ARG1, CA2, F13A1, and S100A12, achieving an mAUROC of 85.3% (72.8–97.8% (95% CI))." (PMID 41155404, 2025). "While the secretome from MPS1i-treated cancer cells has been found to trigger expression of Arg1 and Il6, both of which are pro-cancer M2-like macrophage markers, our findings suggest that polarization is much more complex." (PMID 38805560, 2024). "A phase 1/2 trial of an arginase inhibitor in cancer patients has completed patient recruitment and an arginase 1 peptide vaccine was deemed safe in a phase 1 trial." (PMID 38178089, 2024). "Altogether, our results demonstrate that the acetic acids/FFAR2 axis enhances MDSCs mediated immunosuppression through Gαq/calcium/PPAR-γ/Arg1 signaling pathway, thus contributing to cancer progression." (PMID 38402237, 2024). "In contrast, CCL20 overexpression in cancer cells resulted in an increase in Cox2 and Arg1 expression." (PMID 38297161, 2024). "At day 5 post-challenge, we see that classical M2-like, pro-cancer markers Arg1, Marco, and Cd274 are downregulated." (PMID 37066426, 2024). "While secretome from MPS1i-treated cancer cells has been found to trigger expression of Arg1 and Il6, both of which are pro-cancer M2-like macrophage markers, our findings suggest that polarization is much more complex." (PMID 37066426, 2024).
cancer (continued). "Studies have shown that ARG1 is expressed in endothelial cells and plays crucial roles in various pathological processes, including angiogenesis, wound healing, and cancer." (PMID 39850552, 2024). "In the TME, M1-type antitumor macrophages expressing inducible nitric oxide synthase (iNOS) are polarized into M2-type macrophages expressing arginase 1 (Arg1), thereby promoting cancer cell proliferation and metastasis." (PMID 38339136, 2024). "There is evidence suggesting that the immune tolerance of the uterine cavity during pregnancy, similar to in several cancers, is mediated by the presence of Arg-1-producing MDSCs." (PMID 38592313, 2024). "In recent years, both ARG1 and ARG2 have been linked to many diseases, such as inflammatory, cardiovascular, and neurodegenerative diseases, as well as various cancers, as described in detail in this review." (PMID 39337272, 2024). "Prominently, genes associated with primary liver metabolism, such as ARG1, UGT2R4, and HMGCS2, showed a downregulation rate of 81% in cancer lines." (PMID 39199347, 2024). "During unresolved inflammation in cancer, the most prominent biochemical features implicated in MDSC suppressive activity include increased expression of Arg1, iNOS, NOX-2, and primarily anti-inflammatory cytokines." (PMID 38177412, 2024). "Expectedly, the levels of M2 macrophage-related markers Arg1, p-AMPK, and p-STAT3 showed a tendency to decrease in IDH2-deficient macrophages co-cultured with cancer cells." (PMID 39256649, 2024). "Taken together, the growing body of research on the role of myeloid cell-expressed ARG1 in cancer immune escape underscores the promise of this enzyme as a target for cancer immunotherapy." (PMID 39211039, 2024). "Altogether, these studies indicate that therapeutic targeting of Arg1+ MDSCs, either alone or in combination with existing therapies, can effectively reduce cancer burden and warrants further exploration." (PMID 38464388, 2024). "Based on this observation, we examined the expression profile of Arg1 and HIF1a by mIF imaging in the same ROIs employed for the analysis of the colocalization of Krt8+ cancer cells, CD31+ vasculature, and Col1 1+ protein fibers." (PMID 39372930, 2024). "The suppressive role of MDSCs in cancer mostly contributes to the activation of two enzymes, inducible NO synthase (iNOS) and arginase-1 (ARG1), impeding proliferation and proper functioning of T cells through depletion of L-arginine." (PMID 39877377, 2024). "For this reason, arginase-1 inhibitors have been studied for their potential therapeutic applications in the treatment of cancer." (PMID 39702544, 2024). "ARG1 expression was the most strongly associated with IL1A, NRG1, CCL1, and CRP in cancer str of the CRC tumors among the numerous associated genes (13 401 genes)." (PMID 38557819, 2024). "Arg1+ MDSCs can also be targeted via chemotherapy, one of the four pillars of modern cancer treatment." (PMID 38464388, 2024). "High expression of Arg-1 has been demonstrated in myeloid-derived suppressor cells (MDSCs) in many types of cancer, inhibiting the activity of T-cells." (PMID 38592313, 2024). "Since a reduction in intracellular arginine is known to dampen inflammation and phagocytosis, the high expression of arginase-1 is one of the primary characteristics of M2 polarisation in cancer immunosurveillance." (PMID 36982588, 2023). "Arginase 1 (ARG1) regulates the last step of the urea cycle, and an increase in ARG1 has been correlated as a poor prognostic factor in a variety of cancers." (PMID 37503068, 2023). "Recent results in both tumor mice and cancer patients suggest that increased metabolism of ARG1 by MDSCs inhibits T-cell responses." (PMID 36851096, 2023). "Exploration of this hotspot region identified a 38-aa peptide, ‘ArgLong2’, that activated frequent, strong, and spontaneous ARG1-specific T-cell responses in PBMC samples from heathy donors as well as cancer patients." (PMID 36911725, 2023).
cancer (continued). "Expression of glutaminase 1 (GLS1) is frequently elevated in malignant cells as a result of their metabolic reprogramming, while arginase 1 (ARG1) is secreted from myeloid cells in patients with various cancer types." (PMID 36765849, 2023). "Increased uptake of arginine by cancer cells, and its consumption by TAMs (via arginase-1), reduce its availability in the TME." (PMID 37373581, 2023). "M1 macrophages expressing inducible nitric oxide synthase (iNOS) are regarded as antitumor macrophages, whereas M2-polarized macrophages expressing arginase 1 (Arg1) modulate cancer-related activities, including cancer stemness." (PMID 36838713, 2023). "By utilizing integrated technology coupling single-cell RNA sequencing and intracellular protein activity in a murine cancer model, Katzenelenbogen also clearly demonstrated the highly correlated relationship between Trem2 and Arg1." (PMID 37029450, 2023). "Autophagy plays a key role in cancer cell survival during starvation (low ARG1) and oxidative stress conditions to help the cell find alternative sources of ATP." (PMID 37559065, 2023). "Specially, PMN-MDSCs can suppress cancer-killing cytotoxic mediator secretion in CD8 + T cells through the arginase-1 (Arg-1) and inducible nitric oxide synthase (iNOS) expression." (PMID 37880708, 2023). "The results showed that the concentrations of INOS, IDO, ARG-1 in the peripheral blood serum of patients with malignant tumors was significantly higher than that with benign tumors." (PMID 35725835, 2023). "In this report, we provide 3 important contributions to our understanding of the role of ARG1 in cancer." (PMID 36377658, 2022). "Unlike M1 macrophages, which use Nitric Oxide Synthase 2 (NOS2) to create NO and destroy cancer cells, M2-TAMs metabolize arginine to polyamines through increasing Arginase 1 expression." (PMID 36483029, 2022). "OATD-02, a new boronic acid derivative, is the only dual inhibitor, which can address the benefits of pharmacological inhibition of arginase 1 and 2 in cancer." (PMID 36010962, 2022). "ARG1 is primarily a liver-specific enzyme, but the protein is also highly expressed in several human cancers, including lung, ovarian, renal, breast, and head and neck." (PMID 36330525, 2022). "The future role of an ARG1-based cancer vaccine is rather in an adjuvant setting or in combination with other immunotherapeutic treatment modalities." (PMID 36330525, 2022). "For example, inhibiting protective autophagy promoted the release of arginase 1 (Arg1) from the liver, which promoted arginine synthesis and stimulated cancer cell growth." (PMID 36313710, 2022). "Inhibition of cyclooxygenase-2 (COX-2) with celecoxib has been successful in repressing MDSC-derived Arg1 expression and ROS production, thereby enhancing anti-cancer immune responses." (PMID 35835754, 2022). "ARG1-expressing MDSCs were also shown to induce regulatory T cells (Tregs) in mice and cancer patients." (PMID 36010962, 2022). "Along with the previously validated role of ARG1 in cancer, the particular significance of ARG2 as a therapeutic target has emerged as its levels correlate with malignant phenotype and poor prognosis." (PMID 36010962, 2022). "We have recently found spontaneous effector T cell reactivity against ARG1 peptides in peripheral blood mononuclear cells (PBMCs) of both cancer patients and healthy donors at the National Center for Cancer Immune Therapy (CCIT-DK)." (PMID 36330525, 2022). "A potential mechanism observed is the increase in the expression of arginase-1 (Arg -1) by cancer cells which leads to greater degradation of L-arginine, which is a key nutrient for T and NK cells." (PMID 36499710, 2022). "In the context of cancer, monocytes are quickly differentiated towards M2-like TAMs characterized by higher arginase-1 (Arg1) activity and the surface marker F4/80high CD163+CD206+, suggesting a transition from L-arginine catabolism into depletion." (PMID 36117852, 2022).